ZFP90 (ZFP90 zinc finger protein)
Description:
Inhibits the transcriptional repressor activity of REST by inhibiting its binding to DNA, thereby derepressing transcription of REST target genes. [Isoform 2]: Acts as a bridge between FOXP3 and the corepressor TRIM28, and is required for the transcriptional repressor activity of FOXP3 in regulatory T-cells (Treg).
Synonyms: Zfp-90; KIAA1954; ZNF756; NK10; FIK
Tractability: PROTAC: UniProt records ubiquitination sites on it; ubiquitination databases record sites on it.
Gene: Protein-coding gene on chromosome 16 (68,530,090 to 68,576,072, forward strand). Ensembl gene ENSG00000184939.
Subcellular location: Nucleus
Subcellular location (Human Protein Atlas): Centrosome; Plasma membrane; Vesicles
Pathways (Reactome):
Gene expression (Transcription): Generic Transcription Pathway
Gene Ontology:
Molecular function: protein binding; DNA-binding transcription factor activity, RNA polymerase II-specific; RNA polymerase II transcription regulatory region sequence-specific DNA binding; DNA binding; DNA-binding transcription repressor activity, RNA polymerase II-specific
Biological process: positive regulation of DNA-templated transcription; regulation of transcription by RNA polymerase II; negative regulation of DNA-templated transcription; negative regulation of transcription by RNA polymerase II; regulation of DNA-templated transcription
Cellular component: nucleus
Genetic constraint (gnomAD): Loss-of-function variants: 38 observed, 63.12 expected, observed/expected ratio (o/e) 0.6, 90% interval 0.46 to 0.79. The upper end of that interval is the gene's LOEUF score, 0.79, which puts it in group 3 of 6, group 1 being the genes least tolerant of losing a copy. Missense variants: 711 observed, 797.51 expected, observed/expected ratio (o/e) 0.89, 90% interval 0.84 to 0.95. Synonymous variants: 287 observed, 277.43 expected, observed/expected ratio (o/e) 1.03, 90% interval 0.94 to 1.14.
Homologues: Orthologues: chimpanzee ZFP90 (99% identical), macaque ZFP90 (96% identical), dog ZFP90 (92% identical), pig ZFP90 (91% identical), rabbit ZFP90 (91% identical), guinea pig ZFP90 (89% identical), rat Zfp90 (82% identical), mouse Zfp90 (82% identical), Drosophila melanogaster CG3281 (22% identical), Drosophila melanogaster CG2712 (20% identical), Drosophila melanogaster Phs (19% identical). Paralogues in human: ZNF674 (38% identical), ZNF266 (38% identical), ZFP37 (37% identical), ZNF614 (37% identical), ZNF805 (36% identical), ZNF404 (36% identical), ZNF264 (35% identical), ZNF778 (35% identical), ZNF133 (34% identical), ZNF599 (34% identical), ZNF555 (34% identical), ZNF10 (34% identical), and 50 more.
Diseases named in the same sentence as ZFP90 in open-access papers:
ZFP90 is named in the same sentence as 20 diseases in open-access papers, as found by Europe PMC text mining. Sharing a sentence is not in itself a finding about the gene and the disease. The quoted sentences say what the papers report.
Obesity (5 papers, 2006 to 2023). Accumulation of substantial excess body fat. "Dysregulation of ZFP90 is associated with several diseases including obesity, cardiac dysfunction, and mental retardation." (PMID 31641208, 2020). "This in fact was the case for each of the three genes (Tgfbr2, C3ar1 and Zfp90) we recently reported as being causal for obesity in the BXD cross." (PMID 16886998, 2006). "Later, the literature indicated that Zfp90 contributed to obesity." (PMID 36900383, 2023).
colorectal cancer (3 papers, 2020 to 2023). A primary or metastatic malignant neoplasm that affects the colon or rectum. "The team also expressed that Zfp90 facilitated the development of colitis-associated colorectal cancer via a microbiota-dependent strategy." (PMID 36900383, 2023). "The same research team also discovered that Zfp90 might have played an important role in colitis-associated colorectal cancer (CAC) through the systemic analyses of the GWAS." (PMID 36900383, 2023). "In addition, some studies have also disclosed that Zfp90 played a critical role in initiating colitis-associated colorectal cancer through modulating the nuclear factor of stimulated T-cells and the cytoplasmic 2 (NFATC-2)/bone morphogenic protein-4 (BMP-4) pathway." (PMID 36900383, 2023).
inflammatory bowel disease (2 papers, 2014 to 2021). A spectrum of small and large bowel inflammatory diseases of unknown etiology. "The dysregulation of ZFP90 was associated with some autoimmune diseases, including inflammatory bowel disease, vitiligo, and multiple sclerosis." (PMID 33796098, 2021).
Arthritis (1 paper, 2021). Inflammation of a joint. "Our results also displayed that ZFP90 mRNA expression level was lower in cases with arthritis than without." (PMID 33796098, 2021). "Compared with SLE cases without serositis, arthritis, or hematological involvement, cases with these symptoms had much lower levels of ZFP90 mRNA expression (FDR p = 0.004, FDR p = 0.020, FDR p = 0.021, respectively)." (PMID 33796098, 2021).
cervical carcinoma (1 paper, 2023). A carcinoma arising from either the exocervical squamous epithelium or the endocervical glandular epithelium. "The study indicated that the protein expression of Zfp90 significantly increased when 10μM cisplatin was treated in cervical carcinoma cells (HeLa)." (PMID 36900383, 2023).
ovarian carcinoma (1 paper, 2023). A malignant neoplasm originating from the surface ovarian epithelium. "The intervention of Zfp90 could significantly enhance the apoptosis pathway and inhibit the migrative pathway to regulate the cisplatin sensitivity in ovarian cancer (OC) cells." (PMID 36900383, 2023). "Our study discussed the role of Zfp90 in ovarian cancer (OC) cell lines’ sensitivity to cisplatin." (PMID 36900383, 2023).
systemic lupus erythematosus (1 paper, 2021). An autoimmune multi-organ disease typically associated with vasculopathy and autoantibody production. "A genome-wide association study (GWAS) has discovered that a polymorphism in the ZFP90 gene is associated with systemic lupus erythematosus (SLE)." (PMID 33796098, 2021).
tumor (4 papers, 2015 to 2023). "Our findings revealed the crucial role of the Zfp90-microbiota-NF-κB axis in creating a tumor-promoting environment and suggested therapeutic targets for CAC prevention and treatment." (PMID 33947304, 2021). "Next, we injected different amounts of CRC cells into NOD/Shi-scid/IL-2Rγnull (NSG) mice, and found knockout of ZFP90 reduced HCT116 tumor formation potential." (PMID 31641208, 2020). "ZFP90 is consistently overexpressed in tumor tissues compared with adjacent normal mucosa, and is associated with poor CRC patient survival." (PMID 31641208, 2020). "We observed lower tumor numbers and smaller tumor sizes in Zfp90−/− mice as compared with wild-type mice." (PMID 31641208, 2020). "The growth and the size of tumor organoids were dramatically reduced in Zfp90−/− mice compared with WT mice." (PMID 31641208, 2020). "We have found that knockout of ZFP90 significantly decreased tumor formation capacity in CRC cells." (PMID 31641208, 2020). "In addition, ZFP90 transcriptionally represses the expression of a tumor suppressor, BMP4, and mediates tumorigenesis." (PMID 31641208, 2020). "Furthermore, we detected more Ki67+ proliferative tumor cells in WT mice than Zfp90−/− mice." (PMID 31641208, 2020). "ZFP90 expression was significantly increased in CRC tumor tissues from patients compared with nontumor tissues in Renji cohorts and CRC TCGA datasets." (PMID 31641208, 2020).
cancer (3 papers, 2015 to 2023). A tumor composed of atypical neoplastic, often pleomorphic cells that invade other tissues. "The GO pathway analysis showed that the target genes of ZFP90 were associated with cell proliferation and pathways in cancer." (PMID 31641208, 2020). "Single-sample gene set enrichment analysis (ssGSEA) revealed that the gene sets, which regulated cancer initiation and stemness, were enriched in ZFP90 competent, but not in ZFP90 deficient CRC cells." (PMID 31641208, 2020). "Prior studies also validated that the knockout of Zfp90 could help modulate cancer development." (PMID 36900383, 2023).
colorectal (1 paper, 2020). "Given that GATA2 has been reported as an oncogene, GATA2 expression was increased in ZFP90 knockout HCT116 cells, and ZFP90 knockout blocked colorectal carcinogenesis, we chose BMP4 as the biological candidate target of ZFP90 for validation." (PMID 31641208, 2020).
infection (1 paper, 2021). The state of being infected such as from the introduction of a foreign agent such as serum, vaccine, antigenic substance or organism. "So we would imagine the lower expression of ZFP90 was associated with SLE through the infection pathway." (PMID 33796098, 2021).
ZFP90 also shares sentences with these, for which no sentence is quoted: colitis (2 papers); autoimmune disease (1); colon cancer (1); idiopathic thrombocytopenic purpura (1); multiple sclerosis (1); Parkinson disease (1); rectal cancer (1); ulcerative colitis (1); vitiligo (1).